KRAS (KRas proto-oncogene, GTPase)
Diseases named in the same sentence as KRAS in open-access papers (continued):
Sharing a sentence is not in itself a finding about the gene and the disease.
tumor (continued). "The correlation between KRAS mutation status and various clinicopathological features contributes to a deeper understanding of the potential role of KRAS mutations in tumor development and progression, shedding light on their relationship with different aspects of the disease." (PMID 38465160, 2024). "The tumor has spread to one lymph node (pT3N1 M1c), and genetic analysis reveals the presence of the p.Gly12Asp (c.35G > A) mutation in codon 12 of exon 2 of the KRAS gene within the tumor tissue." (PMID 38745766, 2024). "In KRAS‐mutated lung cancer, tumours with LKB1 mutations silence STING and reduce ICI sensitivity." (PMID 39592436, 2024). "Research suggests that, even before the initiation of panitumumab therapy, resistance mutations in KRAS and other genes may already exist within clonal subpopulations of the tumor, leading to continuous mutation generation." (PMID 39619435, 2024). "KRAS mutations lead to the sustained activation of downstream signaling pathways, which, in turn, result in tumorigenesis, rewire cellular metabolism, and promote alterations in the tumor microenvironment." (PMID 38921460, 2024). "Optimized SYBR Green condition were then performed on the cohort of patients, subdividing them into four groups based on healthy and tumor tissues possessing WT KRAS (KRASGly12, Gly13) or mutated KRAS gene (KRASmut), corresponding to the different types of substitutions in Gly12 or Gly13." (PMID 39722416, 2024). "Therefore, it is crucial to engage in rigorous scientific investigations to establish the generalizability of YAP/TAZ-mediated resistance to KRAS inhibition across a wide spectrum of tumor types and distinct KRAS mutation variants." (PMID 39704172, 2024). "Tumor heterogeneity may also be responsible for the fact that KRAS mutations were found in liquid biopsies but were missed in tumor tissue." (PMID 39064004, 2024). "However, the KRAS G12S mutation detected in this patient had a high allele frequency (21.37%), disproportional to the small tumor size and early tumor stage." (PMID 38310289, 2024). "To validate this molecular crosstalk in a different tumor type driven by KRAS mutations and to verify whether the HIPK2/KRAS cooperation has a causal role in in vivo tumorigenicity, we chose PDAC, the prototype of oncogenic KRAS-driven cancers." (PMID 39342278, 2024). "Additionally, as the tumor analysis was positive for KRAS G12S, we performed mutation analysis of cfDNA using our institution’s gene panel." (PMID 39568077, 2024). "DCs cultured in the PBMCs-IL-2 condition could promote the generation of cytotoxic T cells targeting tumor cells carrying KRAS G12D mutation." (PMID 38554155, 2024). "However, the emergence of CRISPR technology, a groundbreaking gene-editing tool, has revolutionized tumor studies, particularly those focusing on KRAS mutations." (PMID 38275900, 2024). "KRAS gene mutations occurred in almost 86% of tumor samples in four large-scale studies." (PMID 38730578, 2024). "Also, whereas BRAF-mutated tumours displayed increased immune-cell infiltration compared to BRAF wild-type tumours, the opposite was seen for KRAS-mutated tumours, differences that were most prominent for cytotoxic T cells and Th1 cells." (PMID 38040818, 2024). "However, detecting a KRAS mutation via liquid biopsy can be caused by inter-tumor heterogeneity or it can be a false positive due to clonal hematopoiesis." (PMID 39064004, 2024). "Additionally, KRAS mutations remodel the tumor microenvironment by inhibiting anti-tumor immune responses, further promoting tumor progression." (PMID 39433508, 2024). "Additionally, patients with KRAS missense mutations and high Ki67 IHC scores exhibited significantly higher tumor mutational burden levels compared to other groups, which suggests they are more likely to be responsive to ICIs." (PMID 38374309, 2024). "KRAS mutations may also cause PD-L1 overexpression via downstream activation, increase of immunogenicity, and tumor mutation burden (TMB)." (PMID 38397927, 2024).
tumor (continued). "Notably, KRAS mutations can stimulate tumor cell proliferation and growth, which leads to a poor prognosis, while mutations are less abundant in CDN2." (PMID 38461356, 2024). "This association could suggest that KRAS mutations might influence certain tumor patterns of growth." (PMID 38465160, 2024). "Association of KRAS mutant inhibitors (MRTX1133) with marked tumor regression (≥30%) in PDAC." (PMID 39062863, 2024). "KRAS mutation was significantly associated with a high pathological tumor stage in this study." (PMID 39364024, 2024). "KRAS is known to be a strong driver of primary tumor growth, and the mutations are tumor-specific." (PMID 39201772, 2024). "Additionally, oncogenic KRAS mutations have been demonstrated to promote tumor proliferation and survivability by enhancing tumor signaling via metabolic reprogramming and intercommunication with stromal cells." (PMID 39682280, 2024). "As MNAC is an HPV-independent neoplasm, it follows a distinct pathophysiology and has been linked to several genetic mutations, including KRAS/NRAS, ARID1A, ARID1B, SMARCA4, and CTNNB1 mutations, along with chromosomal alterations such as gains of 1q, chromosomes 10 and 12, and loss of 1p." (PMID 39797200, 2024). "Additionally, the presence and quantity of circulating tumor DNA (ctDNA) containing KRAS mutations have been associated with worse overall survival in PDAC patients." (PMID 39456638, 2024). "KRAS mutations are strongly linked to the modulation of tumor inflammation." (PMID 38338768, 2024). "In addition, a 20% PD-L1 tumour proportion was coupled with an Exon 2 KRAS (Kirsten rat sarcoma viral oncogene homolog) mutation." (PMID 39221143, 2024). "Furthermore, the oncogenic KRAS gene mutation not only directly facilitates the proliferation and survival of tumor cells but also exerts an impact on the tumor microenvironment." (PMID 38374309, 2024). "A variant compound significantly reduced tumor volume in KRAS G12D mouse xenograft models." (PMID 38668053, 2024). "KRAS mutations correlated significantly with tumor staging and liver metastases." (PMID 38666907, 2024). "Oncogenic KRAS mutations can dictate the formation of an immune-suppressive tumor microenvironment." (PMID 38216551, 2024). "The most common hotspot mutations in nHM tumours were KRAS p.G12D (15%) and p.G12V (11%)." (PMID 39112715, 2024). "However, in the tumour centre KRAS mutation was significantly associated with increased infiltration of regulatory T cells." (PMID 38040818, 2024). "Loss of the wild-type KRAS allele further promoted tumor cell proliferation and metastasis." (PMID 38666907, 2024). "KRAS mutation was associated with a high pathological tumor stage and nodal involvement." (PMID 39364024, 2024). "HRS-4642 exhibited anti-tumor efficacy in preclinical models as well as a disease control rate (DCR) of 94.4% in a phase I trial enrolling patients with advanced solid tumors harboring KRAS G12D mutations including 10 patients with NSCLC." (PMID 39337530, 2024). "Because lung ADCs with U2AF1S34F frequently have co-occurring KRAS mutations and smoking histories, we hypothesized that tumor-forming potential arises from U2AF1S34F interacting with oncogenic KRAS and environmental stress." (PMID 39314447, 2024). "Besides serving as indicators of prognosis and tumor response, KRAS mutational status in patients with PDAC is also an opportunity for tailored treatment." (PMID 39456638, 2024).
tumor (continued). "KRAS mutation was associated with a high tumor pathological stage." (PMID 39364024, 2024). "The tumor harbored a somatic hotspot activating variant in KRAS p.Gly12Asp." (PMID 39309743, 2024). "Moreover, the action of TGF-beta, especially in PDAC patients with mutated KRAS, drives tumor plasticity." (PMID 38474109, 2024). "Hence, our focus is on these KRAS mutations as potential tumor neoantigens for inducing CTL responses against these malignancies." (PMID 38684865, 2024). "Mutated KRAS promotes uncontrolled cell growth, leading to tumor formation." (PMID 38195537, 2024). "In one case, different KRAS gene mutations were detected in paired tumor samples." (PMID 39273371, 2024). "An interesting study indicated that 45% of CRC-specific mutations (KRAS) in tumor tissues could also be found in their plasma cfDNA in patients and not in healthy groups." (PMID 38770216, 2024). "Moreover, over the years preclinical and clinical studies showed that tumours with KRAS mutations exhibit different treatment sensitivities compared to tumours with wild-type KRAS." (PMID 42064400, 2024). "Interestingly, we also observed significant enrichment and associations for NRAS or KRAS within tumor types such as blood, lymphoid, and ovary." (PMID 39455841, 2024). "However, widely expressed (93% PDAC and 50% CRC) KRAS driver mutations (mKRASs) are attractive immunotherapy targets required for tumor survival with uniform expression throughout disease progression." (PMID 38195752, 2024). "Thus, inhibitors of SHP2 can block the RTK/RAS/MAPK signaling pathways and inhibit the growth and proliferation of tumor cells driven by RTK or with KRAS, BRAF Class 3 and NF1 loss of function mutations." (PMID 39184861, 2024). "Therefore, the observed associations between the expressions of the SEMA7A, SEMA4D, ADAM8, and ADAMTS10 in tumor groups with KRAS, NRAS, BRAF, PIK3CA, and AKT mutations require validation in larger study cohorts." (PMID 39329961, 2024). "Therefore, the prognostic impact of various KRAS mutations including the c.34G>T (p.G12C) mutation should be investigated by future studies with large sample sizes and detailed tumor molecular and treatment data." (PMID 39039804, 2024). "KRAS mutations are detectable across various tumor stages and anatomical locations." (PMID 39768914, 2024). "Homoharringtonine may be a potent immunotherapy drug, against LC associated with Kirsten rats arcomaviral oncogene homolog (KRAS) mutations by directly killing tumour cells and indirectly influencing the TIME." (PMID 38361933, 2024). "Correlations between EGFR and KRAS mutation subtypes and PD-L1 tumor proportion score." (PMID 38394518, 2024). "Some T cells could recognize multiple KRAS mutations, suggesting they could be effective against different tumor types." (PMID 38732150, 2024). "Our analyses may bring some clarity to the matter via integration of our data with existing knowledge, as well as by adding nuance to the overall understanding of KRAS sequence variation and its clinical associations with age of onset and tumor sidedness." (PMID 38032636, 2023). "Third, despite some preliminary evidence for a role of the specific KRAS mutation (i.e., codon 12, 13, or 146) in tumor phenotype, the limited number of studies on this topic did not allow us to examine the association between specific mutation sites of the KRAS gene and treatment response." (PMID 36900260, 2023). "Moreover, evidence has demonstrated resistance to ICIs in NSCLC with KRAS mutation via modulation of tumor metabolism and TME functions." (PMID 36874015, 2023).
tumor (continued). "However, one patient whose tumor had a KRAS G12V mutation experienced a partial response lasting for approximately 20 weeks." (PMID 37894382, 2023). "In the tumor microenvironment, tumor-associated macrophage polarization could be driven by ferroptosis via the release and uptake of the oncogenic KRAS protein." (PMID 37681908, 2023). "Accumulating evidence proved that KRAS mutated tumor cells could affect immune cells infiltration, resulting in tumor progression and immune escape." (PMID 38097680, 2023). "Both 1-2C and 3-2E TCR-T cells could specifically respond to varied tumor cells with the KRAS-G12V mutation, indicating specific recognition of the TCRs to endogenously processed KRAS-G12V-9 peptide in tumor cells." (PMID 37828002, 2023). "In addition, we found that the expression of RAC1, which encodes an important signaling molecule downstream of KRAS pathway, was significantly higher in all three tumor populations." (PMID 37007745, 2023). "The mutation status of KRAS alone is an insufficient indicator of anti-tumor drug resistance as well as overall prognosis, and its specific role remains unclear." (PMID 38097680, 2023). "In addition, our study also showed that the KRAS mutation-positive group had the largest tumor size (2.83 ± 6.87 cm3) relative to ALK (1.23 ± 3.38 cm3) and EGFR (0.51 ± 2.68 cm3) mutation groups." (PMID 37508989, 2023). "KRAS mutations are broadly recognized as promising targets for tumor therapy." (PMID 37828002, 2023). "The authors concluded that it is currently unknown why patients with KRAS mutation exhibit eroded telomeres in tumour tissue." (PMID 37277368, 2023). "In our study, we analyzed the association between germline HRR variants and tumor KRAS status." (PMID 36978154, 2023). "Interestingly, of the 21% (7 out of 29 patients) who achieved PRc/SD > 6 months, one patient had KRAS G12V tumor mutation along with mutations in ARID1A and IDH1." (PMID 38269272, 2023). "The National Comprehensive Cancer Network (NCCN) recommends testing either the primary tumour or the metastatic lesion based on the results ofseveral studies that highlighted high concordance (> 95%) of KRAS mutations between primary CRCs and their matched metastases." (PMID 37670299, 2023). "In addition, because KRAS contains multiple alleles, distinct alleles can alter tumour characteristics." (PMID 36835437, 2023). "The large value of the Interquartile Range may reveal the larger distance in the two percentile values, indicating the high heterogeneity in tumours with KRAS mutation." (PMID 37509345, 2023). "Taken together, these data highlight the need for future studies addressing how the different KRAS-oncogenic mutations alter tumor biology and how this may influence immunotherapy efficacy." (PMID 37370686, 2023). "The patient was treated as carrying a tumor of colorectal origin KRAS mutated (ONCOCARTA result)." (PMID 36346458, 2023). "Several recent studies demonstrated that tumor-associated KRAS mutations, that result in abnormal activation of the RAS/Raf1/MEK/ERK pathway, can lead to multiple defects in the type I IFN signaling, thus making KRASMUT cancer cells more permissive to VSV and other OVs (59, –, 63)." (PMID 37671865, 2023). "Interestingly, KRAS mutations have also been detected in ctDNA, although the primary tumor was considered wild-type." (PMID 36831626, 2023). "In multivariable Cox proportional hazards analyses, COMP expression in the cancer cells (p=0.029) and in the stroma (p=0.021) was associated with reduced patient OS with a hazard ratio of 1.2, after adjustment for BRAF and KRAS mutations, tumor differentiation, TNM-stage, and vascular invasion." (PMID 37207219, 2023).